IGHV3-43 (immunoglobulin heavy variable 3-43)
Description:
V region of the variable domain of immunoglobulin heavy chains that participates in the antigen recognition. Immunoglobulins, also known as antibodies, are membrane-bound or secreted glycoproteins produced by B lymphocytes. In the recognition phase of humoral immunity, the membrane-bound immunoglobulins serve as receptors which, upon binding of a specific antigen, trigger the clonal expansion and differentiation of B lymphocytes into immunoglobulins-secreting plasma cells. Secreted immunoglobulins mediate the effector phase of humoral immunity, which results in the elimination of bound antigens. The antigen binding site is formed by the variable domain of one heavy chain, together with that of its associated light chain. Thus, each immunoglobulin has two antigen binding sites with remarkable affinity for a particular antigen. The variable domains are assembled by a process called V-(D)-J rearrangement and can then be subjected to somatic hypermutations which, after exposure to antigen and selection, allow affinity maturation for a particular antigen.
Synonyms: IGHV343; VH
Gene: Immunoglobulin variable (V) gene on chromosome 14 (106,470,264 to 106,470,800, reverse strand). Ensembl gene ENSG00000232216.
Subcellular location: Secreted; Cell membrane
Gene Ontology:
Molecular function: antigen binding
Biological process: immunoglobulin mediated immune response
Cellular component: extracellular region; plasma membrane
Homologues: Paralogues in human: IGHV3-20 (88% identical), IGHV3-23 (88% identical), IGHV3-74 (86% identical), IGHV3-30 (85% identical), IGHV3-64 (85% identical), IGHV3-64D (84% identical), IGHV3-66 (84% identical), IGHV3-33 (83% identical), IGHV3-48 (83% identical), IGHV3OR16-10 (83% identical), IGHV3-11 (82% identical), IGHV3-53 (82% identical), and 65 more.
Diseases named in the same sentence as IGHV3-43 in open-access papers:
IGHV3-43 is named in the same sentence as 1 disease in open-access papers, as found by Europe PMC text mining. Sharing a sentence is not in itself a finding about the gene and the disease.
IGHV3-43 shares sentences with these, for which no sentence is quoted: periodontitis (1 paper).